CRP (C-reactive protein)
Diseases named in the same sentence as CRP in open-access papers (continued):
Sharing a sentence is not in itself a finding about the gene and the disease.
oral cancer (continued). "In 278 patients with oral cancer, preoperative CRP levels were compared with development of recurrence and metastasis." (PMID 20673375, 2010). "The authors attributed this to the elevated CRP levels observed in oral cancers due to heightened inflammatory activity, which may lower the threshold for the index." (PMID 40941722, 2025). "Although previous studies have reported higher salivary CRP values in OPMDs and oral cancer, none of them has stated a diagnostic cut-off value." (PMID 39851610, 2025). "The oral cancer patients showed the highest level of CRP, with a mean value of 4.21 ng/mL." (PMID 39851610, 2025). "Furthermore, the increase in C-reactive protein level in oral cancer patients was found to be closely related to P. intermedia." (PMID 34956932, 2021). "In this study, we investigated the roles of CRP in different oral cancer subsites." (PMID 28209200, 2017). "All of these data are consistent with the hypothesis that CRP levels increase after onset of oral cancer." (PMID 20673375, 2010). "Post hoc tests showed that the salivary CRP levels were significantly higher in the oral cancer and OPMD groups than in the controls (controls vs. OPMDs: p = 0.01, controls vs. oral cancer: p = 0.001 and OPMDs s." (PMID 39851610, 2025). "The results of the study showed significantly higher values for salivary CRP levels in the OPMD (mean = 2.51 ng/mL) and oral cancer groups, compared to the healthy controls." (PMID 39851610, 2025). "The results of our retrospective analysis showed that low preoperative PNI and high CRP levels were prognostic factors for poorer OS and DFS in patients with oral cancer." (PMID 33482792, 2021). "C-reactive protein (CRP) is an early marker for inflammation, and a relationship between serum CRP levels and survival in oral cancer has been demonstrated previously." (PMID 28209200, 2017). "Although both groups exhibited increased IL-6 and CRP levels postoperatively, without significant differences, further research is needed to validate the efficacy of dexmedetomidine in oral cancer pain management." (PMID 38675500, 2024). "Our results on the differences of the oral bacteria among the groups of dogs and the increase in the CRP, CAR, and NLR suggest that the bacteria and the oral cancer may be related and play a potential role in cancer progression." (PMID 37009523, 2023). "Oral cancer patients with high MMP-9 and CRP levels have had worse prognosis." (PMID 29929486, 2018). "It is still a debate if the elevation of CRP could be due to a concomitant pulmonary infection or other infection, and be non-specific for oral cancer." (PMID 28209200, 2017).
aneurysm (28 papers, 2014 to 2025). Bulging or ballooning in an area of an artery secondary to arterial wall weakening. "CRP is a well-known prognostic marker in various cardiovascular diseases including AAA; in patients with asymptomatic AAA, higher CRP levels are associated with faster aneurysm expansion and increased short-term mortality." (PMID 39737187, 2024). "Considering that AWE is reportedly associated with larger AAA, higher C-reactive protein levels, thicker aneurysm walls, and more severe atheroma, high AWE might be a risk factor for unruptured AAA, similar to the case of intracranial aneurysms." (PMID 33466186, 2021). "In our study, we also found significance in the positive association between CRP and aneurysm diameter (P=0.0009, r=-0.53044), which suggests that patients with bigger AAA present higher levels of CRP; these data might be related to a higher inflammatory activity in AAA with larger diameters." (PMID 34387972, 2021). "Certain biomarkers such as CRP and other inflammatory cytokines were found to positively correlate with increasing aneurysm size and abdominal aneurysm peak wall stress." (PMID 41496900, 2025). "Focal uptake of [18F]FDG was observed in areas of maximal wall stress and in patients with large, rapidly expanding, or symptomatic aneurysms that are prone to rupture together with a systemic increase in circulating C-reactive protein (CRP)." (PMID 38673721, 2024). "Patients with symptomatic or ruptured AAA showed higher circulating levels of CRP and this correlated with an increased aneurysm size." (PMID 37799778, 2023). "The NLR and C-reactive protein concentration showed similar predictive ability for aneurysm size and treatment prognosis." (PMID 33526720, 2021). "In the present study, only a minority of comparisons (i.e. 24%) of CRP and the metabolic activity in the aneurysm showed a similar course in therapy control of patients with INAA." (PMID 33658604, 2021). "In clinical application, there are several reports concerning measuring of plasma biomarkers in attempt to observe aneurysm progression such as C reactive protein (CRP) and IL." (PMID 26166953, 2015). "Given that CRP deposition in our study correlates with enhanced expression of these pathways, we propose that CRP contributes to the progression of inflammation-induced aneurysms." (PMID 39737187, 2024). "In some AAA patients, plasma levels of IFN-γ, IL-17A, and C-reactive protein are positively correlated with the cross-sectional area of AAA, while IL-10 is positively correlated with the growth rate of the aneurysm, and increased CRP levels indicate an increased risk of death in AAA patients." (PMID 38111889, 2023). "This hypothesis is supported bysome of the results, because advanced aneurysms exhibit the greatest CRP levels." (PMID 39076643, 2022). "Areas under ROC of NLR and CRP concentration to predict the aneurysm size and treatment prognosis." (PMID 33526720, 2021). "The relationship between C-reactive protein (CRP) and AAA has been studied, demonstrating a positive relationship between aneurysm-related CRP and the aneurysm’s size, and being a predictor of post-treatment aneurysm progression and a prognostic factor of treatment." (PMID 34387972, 2021). "The upregulation of C-reactive protein (CRP) and interleukin (IL)-6 in patients with AAAs suggests an activation of the inflammatory response system, which has become well-known in aneurysm physiology." (PMID 41496900, 2025). "The results of univariate analysis revealed that the patients with good and poor prognosis had significantly different age, aneurysm diameter, Hunt-Hess grade, timing of surgical treatment and levels of S100B, MCP-1 and CRP (P<0.05)." (PMID 38357151, 2023). "In the vascular wall of AAAs, cytokines such as MCP-1 and c-reactive protein (CRP) are highly secreted in PVAT, promoting VSMC proliferation, elastic arterial stiffness, and accelerating aneurysm formation." (PMID 37007957, 2023).
aneurysm (continued). "Studieshave shown that CRP levels in patients with symptomatic and ruptured AAA aresignificantly higher than in those with asymptomatic aneurysms." (PMID 35072395, 2022). "There is relationship between CRP and AAA, as a predictor of post-treatment aneurysm progression and as a treatment prognostic factor." (PMID 34387972, 2021).
bronchiolitis (28 papers, 2011 to 2025). Inflammation of the bronchioles characterized by swelling of the bronchioles and mucus accumulation. "Previous studies have similarly found that fever, elevated CRP, older age, and increased clinical severity are associated with antibiotic use in children with acute bronchiolitis." (PMID 41153485, 2025). "Persistent high fever, hypoxemia, CRP > 100 mg/L, diffuse bronchiolitis-associated lesions, or whole lobar consolidation on imaging suggested that possible critical MPP would require corticosteroid pulse therapy." (PMID 37082710, 2023). "Another limitation is the scarce number of published studies tackling the association between acute bronchiolitis and CRP levels which made the comparison between the results of our study with those of other studies difficult." (PMID 35655792, 2022). "Data about the association between acute bronchiolitis and CRP levels are scares." (PMID 35655792, 2022). "Patients with severe bronchiolitis were younger, were more likely to have comorbidities, and had higher CRP values compared to the n-IC group." (PMID 40807039, 2025). "In the multivariate analysis, fever on admission (p = 0.002) and CRP ≥ 0.50 mg/dL (p < 0.001) were identified as independent predictors of antibiotic use in children with acute bronchiolitis." (PMID 41153485, 2025). "Our study provides a comprehensive analysis of the early changes in CBC, CRP, and novel inflammatory markers in children with bronchiolitis." (PMID 39861866, 2025). "Possibly, the use of markers such as PCT or CRP should be accompanied by the implementation of clinical practice guidelines to translate well into the management of antibiotics in children with bronchiolitis." (PMID 38133281, 2023). "This variation may reflect their evolving adherence to clinical guidelines, which emphasize that CRP tests often lack predictive value for the severity of bronchiolitis." (PMID 40426750, 2025). "However, on reviewing the literature, no previous study showed the relationship between frequency of fever and cough with the elevated levels of CRP in patients with acute bronchiolitis." (PMID 35655792, 2022). "This study is aimed at assessing the frequency of elevated C-reactive protein (CRP) levels in hospitalized children presented with acute bronchiolitis and at comparing the clinical characteristics, laboratory and radiological findings, antibiotics use, and outcome according to the CRP levels." (PMID 35655792, 2022). "Further studies to figure the critical CRP cut-off that might be of highly suspicious for bacterial infection and to build a clinical management algorithm to minimize the unnecessary use of antibiotics in children with acute bronchiolitis are needed." (PMID 35655792, 2022). "Our results show that in infants with bronchiolitis, RSV, age <6 months, comorbidities (CHD or neurological), BPD, chest indrawing, and C-reactive protein were independent predictors of LOS in a tropical middle-income country." (PMID 35903216, 2021). "To date, a comprehensive analysis of early changes in CBC, CRP, and novel inflammatory markers in determining bronchiolitis severity in infants and children is not reported in the literature." (PMID 39861866, 2025). "Consider use of biomarkers (e.g., FBC, CRP, PCT), urine testing, and blood cultures for the diagnosis of serious bacterial co‐infection for infants with unexpected deterioration during hospitalisation with bronchiolitis." (PMID 40685806, 2025). "In Bahrain, no studies have been published regarding CRP levels in children with acute bronchiolitis." (PMID 35655792, 2022). "Most children with acute bronchiolitis had high rate of elevated CRP values that did not correlate with the rate of bacterial coinfection." (PMID 35655792, 2022).
bronchiolitis (continued). "For this reason, the decision of starting antibiotics in cases of acute bronchiolitis should be taken based on more rigorous evidence such as positive tracheal aspirate, blood, urine, or cerebrospinal fluid cultures rather than high CRP alone." (PMID 35655792, 2022). "This study showed that most patients with acute bronchiolitis had high rate of elevated CRP values that did not correlate with the rate of bacterial coinfection." (PMID 35655792, 2022). "The predictive variables included in the complete model were age, sex, premature birth, comorbidities, BPD, atopy, previously hospitalization by bronchiolitis, %SpO2, fever, signs of respiratory distress, RSV, Leucocytosis (>15.000/mm3) and increased C-reactive protein (>40 mg/lit)." (PMID 35903216, 2021). "It is well documented that routine CRP and blood cultures do notcontribute to the routine management of bronchiolitis, nor assist withthe need for antibiotics." (PMID 34541489, 2018). "Laboratory tests such as C-reactive protein (CRP) and procalcitonin (PCT) can significantly improve the identification of children with an SBI when there is a fever without a source; however, their interpretation is difficult when there is overlapping bronchiolitis." (PMID 39200002, 2024). "However, elevated serum CRP levels have been witnessed in children with acute bronchiolitis in the absence of a confirmed bacterial coinfection or the need of antibiotic used." (PMID 35655792, 2022).
endocarditis (28 papers, 2007 to 2025). Inflammation of the endocardium. "The presence of endocarditis, septic shock, and an elevated CRP level at presentation were risk factors for un-favorable outcome at the end of teicoplanin therapy." (PMID 23601053, 2013). "Of the laboratory parameters of inflammation, the level of CRP on admission was most prominently associated with the outcome of endocarditis throughout the study period, the prognosis being significantly worse in the patients with high CRP values." (PMID 17640339, 2007). "Our data suggest that once the CRP levels in clinically stable patients are decreasing steadily, patients across a variety of endocarditis causes may be eligible for outpatient parenteral treatment." (PMID 34524621, 2022). "Patients with Bartonella quintana endocarditis reported in Ethiopia, Guinea, and other regions all showed elevated CRP levels." (PMID 39600931, 2024). "Endocarditis was excluded with blood cultures, c-reactive protein (CRP), and histology of this valve." (PMID 38124891, 2023). "Our univariate analysis demonstrated a relationship between CRP > 16 mg/dL and endocarditis complications." (PMID 32346051, 2020). "A new finding was that high CRP values on admission significantly predicted both short-term and 1-year mortality in endocarditis." (PMID 17640339, 2007). "Elevated and persistent CRP levels with or without fever may reflect ongoing disease activity, and renewed CRP elevation in the later phase may reflect new inflammatory activity, more likely other than endocarditis." (PMID 39499433, 2024). "Thomas’ suggested minor criteria, our study showed elevated CRP in 76.3%, elevated ESR in 21.1%, hematuria in 13.2% and indwelling CVC in 34.2% of cases of NGNB endocarditis." (PMID 37235331, 2023). "Data on the serum CRP value, ESR, WBC count, and serum creatinine value on admission was available in 205, 149, 217, and 218 episodes of endocarditis, respectively." (PMID 18419812, 2008). "Data on serum CRP value, ESR, WBC count, and serum creatinine value on admission was available in 272, 192, 290, and 282 episodes of endocarditis, respectively." (PMID 17640339, 2007). "Third, ESR/CRP values did not appear to influence decision-making outside of bone and joint infections or endocarditis, and perhaps these labs should be avoided for other OPAT indications." (PMID 40109915, 2025). "Some of these diseases can also increase CRP and reduce albumin, so it can be difficult to distinguish whether abnormal GPS is due to endocarditis or its complications." (PMID 39292095, 2024). "Our study demonstrates the value of monitoring the CRP area under the curve when spondylodiscitis itself shows a prolonged period of elevated CRP levels without endocarditis complications." (PMID 39499433, 2024). "In a recent meta-analysis with 6 trials (1006 episodes of suspected endocarditis), the global measures of accuracy of CRP were higher than PCT showing that current evidence does not support the routine use of serum PCT or CRP to rule in or rule out endocarditis." (PMID 24800240, 2014).
hip fracture (28 papers, 2012 to 2026). Traumatic or pathological injury to the hip in which the continuity of either the femoral head, femoral neck, intertrochanteric or subtrochanteric regions is broken. "Recent studies have identified IL-6, IL-8, CRP, and C1q as independent risk factors for poor postoperative joint function in hip fracture patients." (PMID 40182857, 2025). "In a retrospective analysis involving 278 elderly hip fracture patients, Wang observed that decreased perioperative serum albumin levels and increased C-reactive protein (CRP) levels were associated with adverse postoperative events." (PMID 39536046, 2024). "Several biochemical markers of inflammation, such as levels of CRP, the soluble urokinase plasminogen activating receptor (suPAR) and ferritin, were found to be associated with 30-day mortality after hip fracture." (PMID 33663402, 2021). "Among routine laboratory blood tests that we assessed as secondary outcome, low Hb, albumin, and TLC, and high creatinine, potassium, troponin T, and CRP have all been reported be associated with poor outcome in hip fracture patients." (PMID 32466360, 2020). "Several studies have shown that 30-day mortality after a hip fracture is associated with elevated inflammatory cytokines, such as C-reactive protein, interleukin (IL)-6, IL-8, tumor necrosis factor-α, and soluble urokinase plasminogen activating receptor." (PMID 32850880, 2020). "Preoperative immune-inflammatory indicators, such as the neutrophil-to-lymphocyte ratio (NLR), platelet-to-lymphocyte ratio (PLR), monocyte-to-lymphocyte ratio (MLR), and CRP, are associated with increased all-cause mortality after surgery in elderly hip fracture patients." (PMID 40182857, 2025). "We hypothesized that low levels of 25(OH)D and elevated levels of CRP are associated with increased postoperative medical complications and one year mortality of elderly patients that sustained a low-energy hip fracture." (PMID 26833068, 2016). "National hip fracture database (NHFD) data, including the NHFS, were linked with admission biomarkers: albumin, C-reactive protein (CRP), neutrophil-lymphocyte ratio (NLR) and monocyte-lymphocyte ratio (MLR)." (PMID 40275223, 2025). "Four of the 14 studies, involving 1255 patients with hip fracture, compared postoperative CRP levels between the death and survival groups for a follow-up duration of ≥ 6 months." (PMID 36894998, 2023). "Observational studies investigating the correlation between perioperative CRP level and postoperative mortality in patients with hip fracture were included." (PMID 36894998, 2023). "High preoperative levels of serum CRP (>10 mg/dL) and low levels of serum albumin (<3 g/dL) are widely considered independent predictors of mortality after hip fracture in the elderly population." (PMID 37445579, 2023). "In our meta-analysis, those who died following hip fracture exhibited higher levels of CRP preoperatively and postoperatively, suggesting a higher degree of inflammation during the perioperative period in these patients." (PMID 36894998, 2023). "Our findings suggest the prognostic role of CRP in patients with hip fracture and its additional applications for orthopedic surgeons in clinical practice." (PMID 36894998, 2023). "In our investigation of the correlation between preoperative CRP level and long-term hip fracture mortality, significant heterogeneity (I2: 73%, P < 0.1) was detected." (PMID 36894998, 2023). "Further research is warranted to evaluate the ability of CRP to predict postoperative mortality in patients with hip fracture." (PMID 36894998, 2023). "Further studies are warranted to confirm the ability of CRP to predict postoperative mortality in patients with hip fracture." (PMID 36894998, 2023). "The TMAO serum levels also related to high-sensitivity C-reactive protein (r=0.212, P<0.001) and Ca (r=0.186, P=0.003) in hip fracture patients." (PMID 32482913, 2020).